RNU6-178P (RNA, U6 small nuclear 178, pseudogene)
Gene: Small nuclear RNA gene on chromosome 8 (28,416,448 to 28,416,551, forward strand). Ensembl gene ENSG00000207361.
Homologues: Orthologues: chimpanzee U6 (99% identical), macaque U6 (95% identical), rabbit U6 (76% identical), rabbit U6 (75% identical). Paralogues in human: RNU6-1060P (86% identical), RNU6-116P (86% identical), RNU6-708P (86% identical), RNU6-1011P (85% identical), RNU6-1117P (85% identical), RNU6-12P (85% identical), RNU6-13P (85% identical), RNU6-166P (85% identical), RNU6-32P (85% identical), RNU6-33P (85% identical), RNU6-41P (85% identical), RNU6-47P (85% identical), and 1289 more.